AQP4 (aquaporin 4)
Diseases named in the same sentence as AQP4 in open-access papers (continued):
Sharing a sentence is not in itself a finding about the gene and the disease.
Constipation (7 papers, 2022 to 2025). Infrequent or difficult evacuation of feces. "Clone aquaporins, particularly AQP3 and AQP4, play crucial roles in water transport and are potential targets for constipation prevention." (PMID 41517161, 2025). "Our results showed that AQP4 and AQP8 expression in the colon of constipation mice was significantly higher than that of normal mice, while AQP4 and AQP8 expression was significantly down-regulated in the colon of three intervention groups." (PMID 36687730, 2022). "Rats fed with bacterial cellulose, a naturally occurring DF derived from bacteria, improved constipation symptoms, shortened defecation periods, increased feces weight, and decreased levels of inhibitory neurotransmitters and AQPs (AQP2, AQP3, and AQP4) in comparison to the constipation group." (PMID 40807605, 2025). "Emerging evidence indicates that dysregulated expression of colonic aquaporins (e.g., AQP3 and AQP4) may lead to excessive colonic water absorption and/or reduced secretion of intestinal fluid, thereby contributing to the pathogenesis of constipation." (PMID 41154071, 2025). "The RT-PCR and immunohistochemical experiment showed that all three interventions relieved constipation by affecting aquaporins (AQP4 and AQP8), interstitial cells of Cajal (SCF and c-Kit), glial cell-derived neurotrophic factor (GDNF), and Nitric Oxide Synthase (NOS)." (PMID 36687730, 2022). "In the constipation mouse model, the expressions of AQPs have changed, including upregulated AQP3, AQP4, and AQP8, and downregulated AQP9." (PMID 40807605, 2025). "Another study also indicated that the yellow tea extract consumption protected against operamide-induced constipation in mice partially through the upregulation of 5-HT3 and 5-HT4 expression and downregulation of AQP3 and AQP4 expression in the colon." (PMID 38089478, 2023). "We detected the expression of AQP by RT-PCR and IHC and found that the expressions of AQP4 and AQP8 in the intestines of mice in the constipation group were significantly increased." (PMID 36687730, 2022). "The result showed that the protein levels of AQP4 and AQP8 in the colon of constipation mice were significantly higher than those in the normal group." (PMID 36687730, 2022). "However, mulberry (Morus atropurpurea) fruit had a protective effect against diphenoxylate-induced constipation through modulation of gut microbiota and decreased expression of AQP3, AQP4, AQP8, and AQP9 in the colon of mice." (PMID 38089478, 2023). "Generally, the increased expression of AQP4 and AQP8 is observed in mouse constipation models." (PMID 36904145, 2023).
glaucoma (7 papers, 2008 to 2022). Increased pressure in the eyeball due to obstruction of the outflow of aqueous humor. "Genetic deletion of AQP4 leads to increased brain extracellular volume and AQP4 was reported to be downregulated in the optic nerve in rat glaucoma." (PMID 35709078, 2022). "While no gene changes were noted after one hour IOP increase in mouse, optic nerve crush was reported to lead to decreased AQP4 expression, while in DBA/2J mouse glaucoma, AQP4 rose in a small number of nerves." (PMID 33529207, 2021). "Here we describe a case of successful trabeculotomy performed on a patient with corticosteroid-induced glaucoma and anti-aquaporin 4 antibody-positive NMO." (PMID 23575376, 2013). "This was a rare case in which the initial main cause of our patient’s visual disturbance was likely anti-aquaporin 4 antibody-positive NMO, but the critical treatment for her visual improvement appeared to be trabeculotomy against glaucoma." (PMID 23575376, 2013). "We tested the hypothesis that AQPs were critical to glaucoma damage by study of genetic deletion of AQP4 in short and medium-term glaucoma models in mice." (PMID 33529207, 2021). "For example, Aqp4, astrotactin 1 (Astn1), contactin 1 (Cntn1), and gap junction protein alpha 1 (Gja1) were down-regulated after optic nerve crush, but were up-regulated in glaucoma." (PMID 23826199, 2013). "The enhanced expression of AQP4 in optic nerve astrocytes following elevation of IOP may explain the astrocytic hypertrophy normally seen in glaucoma patients and may involve alteration in the activity of ubiquitin-dependent proteasomal degradation system." (PMID 18836575, 2008). "Genetic deletion of AQP4 leads to increased brain extracellular volume and AQP4 was downregulated in the ONH region in a chronic rat glaucoma model." (PMID 33529207, 2021). "Because corticosteroid therapy is a first-choice therapy for anti-aquaporin 4 antibody-positive NMO, we should expect corticosteroid-induced glaucoma as a potential complication of the therapy." (PMID 23575376, 2013). "Corticosteroid therapy is a first-choice treatment for anti-aquaporin 4 antibody-positive NMO, and corticosteroid-induced glaucoma is a potential complication of this therapy." (PMID 23575376, 2013). "This evolutionarily conserved regional lack of AQP4 at the UON has potentially important implications for how the ON is protected in glaucoma." (PMID 33529207, 2021). "With similar IOP elevation levels, AQP4 null mice did not have either a beneficial or a detrimental effect on experimental glaucoma parameters." (PMID 33529207, 2021). "While it is clear that astrocytic reaction in glaucoma involves a variety of changes in these glia, the participation of AQP4 channels in fluid movements in the retina and optic nerve seems not to play a vital role in experimental glaucoma damage." (PMID 33529207, 2021). "Recent investigations have suggested that AQP4 deletion could impair the removal of fluid and metabolites and that AQP functions could be involved in glaucoma pathogenesis." (PMID 33529207, 2021). "The function of AQP4 as a water channel and its intriguing expression pattern at the ONH may make it relevant in glaucoma." (PMID 23826199, 2013). "We hypothesize that the normal lack of AQP4 at the site of typical glaucoma damage in all animals yet studied is likely to be an evolutionarily conserved, regionally specific phenotype of ONH astrocytes." (PMID 35709078, 2022). "However there are no reports describing corticosteroid-induced glaucoma and its treatment in the context of a patient with anti-aquaporin 4 antibody-positive NMO." (PMID 23575376, 2013). "The minimal presence of AQP4 at the large animal lamina and the unmyelinated nerve of rodent eyes is highly evolutionarily conserved and therefore may be either advantageous for normal ONH function, and/or a protective influence for retinal ganglion cell axons from glaucoma damage." (PMID 35709078, 2022).
glaucoma (continued). "Immunolabeling of human glaucoma eyes found reduced AQP9 in retinal ganglion cells, but presence or change in AQP4 in the ONH was not described." (PMID 33529207, 2021).
intracranial hypertension (7 papers, 2017 to 2025). A finding characterized by increased cerebrospinal fluid pressure within the skull. "Since AQP4 is expressed at multiple sites in the CNS, including many regions from retinal astrocytes to perinodal axolemma of optic nerve, we may speculate on the possible visual damage associated with intracranial hypertension if IIH was bounded to AQP4 deficiency." (PMID 29387036, 2017). "Failure of any axis will cascade and affect the entire axis, linking venous congestion, aquaporin-4 disassembly, and meningeal lymphatic failure to protein aggregation, neuroinflammation, edema, and intracranial hypertension." (PMID 41226584, 2025). "In the present study, we demonstrated that the upregulation of AQP4 and HIF-1α contributes to brain edema formation, a critical process involved in intracranial hypertension and cerebral hernia following traumatic brain injury (TBI)." (PMID 35177771, 2022).
Myelopathy (7 papers, 2012 to 2025). Myelopathy is an descriptive term, referring to pathology leading to a neurologic deficit related to the spinal cord. "passive transfer of specific human AQP4-ABs or purified IgG fractions from NMOSD patients (NMO-IgG), that ABs can induce signs of myelopathy and cause a reduction of astrocyte surface expression of AQP4." (PMID 27571069, 2016). "Autoantibodies with strong clinical correlation to neurological disease in SLE are the aPL (observed in our study in 8/16 patients), the anti-ribosomal P antibodies (2/16 patients), and the NMO-IgG/anti-AQP4 antibodies that appeared in 2 out of 4 patients with myelopathy." (PMID 23424638, 2013). "Myelopathy correlated with lower disease activity scores and the presence of NMO-IgG/anti-AQP4 antibodies (P≤0.05)." (PMID 23424638, 2013). "We also chose to exclude patients with longitudinal myelopathy attributed to SLE (i.e., anti-aquaporin-4 negative)." (PMID 35645967, 2022).
neurosarcoidosis (7 papers, 2023 to 2025). A sarcoidosis that involves the nervous system. "Controls included non‐inflammatory (N = 42), AQP4‐IgG‐positive (N = 83), CNS infections (N = 13), and neurosarcoidosis (N = 32)." (PMID 39869499, 2025). "Longitudinally extensive inflammatory myelitis comprises a wide range of pathologies including AQP4 + NMOSD, MOGAD, neurosarcoidosis, ADEM, or neuro-Behçet’s disease." (PMID 38473365, 2024).
Obesity (7 papers, 2017 to 2025). Accumulation of substantial excess body fat. "Some of the highly synthesized IgG autoAbs that were depleted in the BAFF-neutralized mice target C-reactive protein, tissue transglutaminase, aquaporin 4, and complement C1q, and these proteins are associated with obesity-induced WAT inflammation and increase in IR." (PMID 39185417, 2024). "Indeed, there seems to occur the clearance saturation of the glymphatic system, whether by a primary disturbance (e.g., AQP4 deficiency) or, for example, by an increase in volume of the PVSs, which could take place in inflammatory conditions such as obesity." (PMID 29387036, 2017). "We aimed to investigate a possible association between obesity (body mass index [BMI] > 30 kg/m2) in patients with MOGAD, aquaporin 4-IgG positive NMOSD (AQP4-IgG+ NMOSD) or MS." (PMID 36494385, 2022). "In patients with acute ON, obesity was associated with a higher odds ratio (OR) of subsequent MOGAD diagnosis (OR 5.466, 95% CI [2.039, 14.650], p = 0.001) compared with AQP4-IgG+ NMOSD." (PMID 36494385, 2022). "Our study suggests that there is an association between obesity and MOGAD in a retrospective study of 183 patients: 44 with MOGAD, 49 with AQP4-IgG+ NMOSD, and 90 with MS." (PMID 36494385, 2022). "Our findings indicate that AQP4-inhibited mice exhibit MRI values consistent with reduced microvascular blood flow and region-specific inhibition of glucose-induced cell swelling during obesity, highlighting a key role for AQP4 in glucose uptake and metabolism." (PMID 40325102, 2025). "Mixed-effects multinomial logistic regression, adjusted for age and sex, with obesity as a binary variable, revealed that obesity was associated with a higher odds ratio (OR) of a subsequent MOGAD diagnosis (OR 5.466, 95% CI [2.039, 14.650], p = 0.001) in contradistinction with AQP4-IgG+ NMOSD." (PMID 36494385, 2022). "A mixed model analysis was performed to assess the potential of obesity or BMI to predict MOGAD-ON, and to distinguish MOGAD-ON from AQP4-IgG+ NMOSD-ON and MS-ON." (PMID 36494385, 2022). "Prior studies have suggested that obesity may play a predisposing risk factor for MS5–7, but this has not been explored in aquaporin 4-IgG positive NMOSD (AQP4-IgG+ NMOSD) or MOGAD." (PMID 36494385, 2022).
Optic neuropathy (7 papers, 2021 to 2025). "Cases with alternative causes of optic neuropathy, including myelin oligodendrocyte glycoprotein antibody (MOG) IgG or aquaporin-4 antibody (AQP4) IgG-associated disease, were excluded." (PMID 41446483, 2025). "A similar diagnostic approach to optic neuropathy applies here, including testing for ANA, aPL, anti-ribosomal P protein, anti-Ro60/SSA, anti-La/SSB, anti-aquaporin 4 (AQP4), anti-myelin oligodendrocyte glycoprotein (MOG), and ANCA." (PMID 39204149, 2024). "In conclusion, atypical optic neuropathy seronegative for AQP4 and MOG antibodies, combined with vitreitis, retinitis, or uveitis, should prompt serological testing for CRMP5 antibody." (PMID 37448746, 2023). "Therefore, NMO should be considered and serum AQP4 Ab levels should be tested in MG patients with clinical signs or symptoms indicative of NMO; these include spinal cord and optic neuropathy, and brainstem symptoms such as intractable vomiting, narcolepsy or hiccoughs." (PMID 37781409, 2023). "When there is no confirmed macroscopic structural damage that can explain the visual impairment, the positivity of serum AQP4‐IgG would be better to be checked before making a definite diagnosis of traumatic optic neuropathy and deciding not to use the steroids." (PMID 33591639, 2021).
overlap syndrome (7 papers, 2017 to 2025). "The clinical manifestation of GFAP astrocytopathy is complex; moreover, it can coexist with a variety of antibodies, including aquaporin-4 (AQP4) antibody and N-methyl-D-aspartate receptor (NMDAR) antibody and is, therefore, called overlap syndrome." (PMID 39464885, 2024). "The contemporaneous detection of AQP4- and AGO-Abs led to a definite diagnosis of overlap syndrome of NMOSD with AGO-Abs." (PMID 38887290, 2024). "In addition, no patients with overlap syndrome in our study were found to have anti-AQP-4 antibodies, which may be because NMOSD was relatively rare in our study population (anti-AQP-4 is an important biological marker of NMOSD)." (PMID 36401212, 2022).
sarcoidosis (7 papers, 2018 to 2024). Sarcoidosis is a multisystemic disorder of unknown cause characterized by the formation of immune granulomas in involved organs. "Sarcoidosis and AQP4+NMOSD represent the inflammatory myelopathies most often misdiagnosed as spinal cord malignancies (ependymomas in the case of AQP4+NMOSD) given their association with spinal cord swelling." (PMID 36330423, 2022). "Immunosuppressive strategies frequently used to treat AQP4-ON, MOG-ON, neuro-sarcoidosis, and CRION include azathioprine, methotrexate, mycophenolate mofetil, rituximab, and infliximab; rescue immunomodulatory therapies - immunoglobulin and plasma exchange - may also be needed." (PMID 38867071, 2024).
syphilis (7 papers, 2019 to 2025). A contagious bacterial infection caused by the spirochete Treponema pallidum. "Except for one patient who was diagnosed with syphilis-related ON, all patients underwent tests for MOG antibodies and AQP4 antibodies using cell immunofluorescence method." (PMID 38988608, 2024).
transient cerebral ischemia (7 papers, 2010 to 2024). "AQP4, the most abundant channel in the brain, is up-regulated around the peri-infarct border in transient cerebral ischemia and AQP4 knockout mice demonstrate significantly reduced cerebral edema and improved neurological outcome." (PMID 25904843, 2015). "In a mouse model of transient cerebral ischemia, AQP4 expression was rapidly up-regulated in perivascular end-feet, reaching a peak 1 h post-occlusion and coinciding with early cerebral swelling in the core and border of the lesion." (PMID 25904843, 2015). "Additionally, AQP4-knockout mice exhibited neuroprotection and improved inflammation due to reductions in brain edema in transient cerebral ischemia." (PMID 39335590, 2024). "Double-staining for AQP4 and GFAP was performed to assess the functional changes induced by transient cerebral ischemia-reperfusion and sildenafil treatment in the hippocampus by BBB disruption." (PMID 39335590, 2024). "The expression profiles of AQP4 and AQP9 in edema were recently studied at various time points after mouse transient cerebral ischemia to gain insights into their role." (PMID 21119881, 2010).
vasculitis (7 papers, 2010 to 2025). "When clinicians encounter a patient with ON complicated with vasculitis, serum anti-AQP4 antibodies, and anti-MOG antibodies should be assessed, which might help obtain an accurate diagnosis." (PMID 33847609, 2021). "ANAs or other inflammatory mechanisms in CTD may contribute to vascular damage and disruption of the BBB induced by vasculitis, which makes the AQP4-IgG accessible to the CNS and triggers the AQP4-IgG-mediated inflammatory cascade." (PMID 30355349, 2018). "However, in vasculitis and in retinal inflammatory lesions, the characteristic radial labeling of AQP4 observed in controls was lost." (PMID 20383338, 2010). "In vasculitis and intraretinal inflammatory infiltrates, decreased AQP1 expression was observed due to the loss of photoreceptors and the characteristic radial labeling of AQP4 was lost." (PMID 20383338, 2010). "Therefore, it was considered that in patients with NMOSD and CTD, central nervous system damage is secondary to astrocytic lesions caused by AQP4-IgG rather than vasculitis in SS or SLE." (PMID 36090884, 2022). "In SLE, spinal cord injury may result from vasculitis, thrombosis, or direct antibody-mediated inflammation, whereas NMOSD is primarily an astrocytopathic process driven mainly by anti-AQP4 antibodies." (PMID 41431554, 2025).
Atrophy (6 papers, 2013 to 2025). Any weakening or degeneration, especially through lack of use. "The atrophy subtypes of AQP4 + NMOSD have multiple implications for interpreting NMOSD heterogeneity." (PMID 40898200, 2025). "Specifically, the atrophy trajectory among AQP4 + NMOSD patients across various atrophy subtypes sheds light on potential patterns of disease progression, offering a novel perspective for understanding the subtle brain tissue damage in AQP4 + NMOSD patients." (PMID 40898200, 2025). "Our results show that patients with AQP4 + NMOSD had significantly higher annualized NWV atrophy rates than age-sex-matched HCs." (PMID 37537208, 2023). "This occurred in only 17% of patients with AQP4-Ab disease, in whom residual lesions or atrophy were more common." (PMID 31596489, 2019). "Our results confirmed the key role of AQP4 expression for the presence of brain lesions and atrophy, but were also able to identify the relevant biological pathways, including the activation of the complement cascade, the regulation of IGF and uptake by IGFBPs, and IL-4, -13, and -10 signaling." (PMID 39891565, 2025). "Patients with AQP4 + NMOSD had a greater annualized NWV atrophy rate than HCs." (PMID 37537208, 2023). "Patients with AQP4 + NMOSD had higher annualized NWV atrophy rates than HCs." (PMID 37537208, 2023). "OCT was used to test for atrophy of the optic nerve; AQP4 antibodies were also detected." (PMID 24950188, 2014). "OCT was used to test for atrophy of the optic nerve, and AQP4 antibodies were also detected." (PMID 24950188, 2014). "Additionally, three NMO patients (all anti-AQP4 seropositive) had severe general atrophy of the spinal cord." (PMID 24348680, 2013). "In AQP4 + NMOSD, T2-hyperintense lesions were mainly periventricular; atrophy mostly involved the visual pathway." (PMID 39891565, 2025). "No voxels of significant atrophy were found in HC compared with AQP4 + NMOSD patients." (PMID 39891565, 2025). "Complete resolution of abnormalities in MRI findings, without atrophy, occurred in 16 patients (62%) with MOG-Ab disease and 7 patients (17%) with AQP4-Ab disease (P < .001)." (PMID 31596489, 2019). "Notably, some AQP4 + NMOSD and MS patients without apparent CNS atrophy had disease relapses and disabilities similar to those with atrophy." (PMID 40898200, 2025).